SCD (stearoyl-CoA desaturase)
Diseases named in the same sentence as SCD in open-access papers (continued):
Sharing a sentence is not in itself a finding about the gene and the disease.
viral infection (6 papers, 2018 to 2025). "Viral infections can significantly alter cellular lipid metabolism by modulating key rate-limiting enzymes, including fatty acid synthase (FASN), stearoyl-CoA desaturase 1 (SCD1), and acetyl-CoA carboxylase (ACC)." (PMID 40387378, 2025).
acute myeloid leukemia (5 papers, 2021 to 2026). Acute myeloid leukemia (AML) is a group of neoplasms arising from precursor cells committed to the myeloid cell-line differentiation. "In Acute Myeloid Leukemias (AML), FLT3 inhibitors enhance the sensitivity of FLT3-mutant AML cells to lipid oxidative stress by inhibiting the C/EBPα/SCD axis, thereby inducing ferroptosis." (PMID 40093329, 2025).
esophageal cancer (5 papers, 2013 to 2025). A primary or metastatic malignant neoplasm involving the esophagus. "Inhibition of SCD suppresses oesophageal cancer progression displayed in vitro with reduced colony formation and in vivo with decreased tumour volume." (PMID 40381373, 2025). "Microarray results showed the influence of SFE on esophageal cancer cells was related with stearoyl-CoA desaturase (SCD), cadherin 3 (CDH3), mitogen-activated protein kinase kinase 3 (MAP2K3) and growth arrest and DNA damage inducible beta (GADD45B)." (PMID 32873775, 2020). "We had proven that SFE could significantly inhibit esophageal cancer cell progression, and SCD and CDH3 were involved in SFE inhibition of cell metastasis, yet the mechanism by which SFE inhibited cell proliferation was still unclear." (PMID 32873775, 2020). "SCD is upregulated in tumor cells, including colonic and esophageal carcinoma." (PMID 24935936, 2014). "In short, SFE inactivated the Wnt pathway by downregulating SCD and CDH3 expression to suppress esophageal cancer cell metastasis." (PMID 32873775, 2020). "Then we verified SFE could inactivate the Wnt pathway while SCD and CDH3 overexpression reactivated it in esophageal cancer cells." (PMID 32873775, 2020). "In this study, we showed that SFE could inactivate it through inhibiting SCD and CDH3 expression to regulate esophageal cancer cell metastasis." (PMID 32873775, 2020). "Proving SFE could decrease SCD and CDH3 expression in vitro and in vivo, we identified SCD and CDH3 were the targets of SFE in esophageal cancer cells." (PMID 32873775, 2020). "Next, we tested whether SCD and CDH3 played an important role in esophageal cancer cells." (PMID 32873775, 2020).
Hypercholesterolemia (5 papers, 2012 to 2020). An increased concentration of cholesterol in the blood. "However, side effects have been also reported, including hypercholesterolemia, problems in reproduction or carcinogenesis due to SCD activity inhibition." (PMID 32403229, 2020).
Hyperinsulinemia (5 papers, 2011 to 2020). An increased concentration of insulin in the blood. "Furthermore, it has been described that the hepatic SCD-1 activity can be modified with high carbohydrate diets, dietary energy restriction, alcohol consumption, hyperinsulinemia, estrogens or physical exercise." (PMID 32630591, 2020). "The state of hyperinsulinemia increases the activity of SREBP in the liver, thereby increasing the levels of lipogenic genes, such as fatty acid synthase (FAS), acetyl-CoA carboxylase (ACC) and Stearoyl-CoA Desaturase1 (SCD1) contributing to the buildup of hepatic fat." (PMID 23496920, 2013).
lymph node metastasis (5 papers, 2016 to 2024). "We have revealed that SCD is notably overexpressed in Caucasian patients, as well as in patients with Gleason score 8, stage N1 lymph node metastasis, or ERG fusion." (PMID 39351232, 2024). "Lastly, the presence of lymph node metastasis correlated with elevated risk scores and DDR2 expression but not with SCD and MT1A." (PMID 39107713, 2024).
nonalcoholic steatohepatitis (5 papers, 2017 to 2023). "While SCD has been shown to be a crucial factor in the lipid metabolism and body weight control, its inhibitors are claimed to be beneficial for the treatment of different diseases, such as skin disorders, nonalcoholic steatohepatitis (NASH), HCV, Alzheimer’s disease, or cancer." (PMID 35053112, 2022).
Sepsis (5 papers, 2020 to 2025). Sepsis is defined as life-threatening organ dysfunction caused by a dysregulated host response to infection. "Inhibition of SCD-1 can lead to inflammation-associated sepsis." (PMID 36014961, 2022).
bipolar disorder (4 papers, 2011 to 2024). A disorder of the brain that causes unusual shifts in mood, energy, activity levels and the ability to carry out day-to-day tasks. "Previously studies have documented a progressive increase in MUFA levels and SCD-1 expression in human frontal cortex during normal aging and in patients with bipolar disorder." (PMID 22046234, 2011).
Cognitive impairment (4 papers, 2011 to 2024). Abnormal cognition is characterized by deficits in thinking, reasoning, or remembering. "Despite these limitations, our study does point to a previously unrecognized connection between cognitive impairment in AD and up-regulation of the lipogenic enzyme SCD." (PMID 22046234, 2011). "Higher FA levels and SCD activity have been shown to correlate closely with cognitive impairment." (PMID 30373213, 2018). "Using an untargeted lipidomic strategy, we found that the levels of nervonic acid and other MUFAs produced by SCD are markedly elevated in frozen brain samples from AD patients, compared to age-matched control subjects, and that these changes strongly correlate with cognitive impairment." (PMID 22046234, 2011).
depression (4 papers, 2022 to 2025). "Some might argue that certain negative affective factors, like depression, should be treated as confounding factors, however, the guidelines in the field of SCD suggest otherwise as it provides an incomplete understanding of the expression of SCD1,2." (PMID 35418579, 2022).
diabetic nephropathy (4 papers, 2016 to 2024). "Bailing Capsule activated the expression of PPARα, ACOX1 (acyl-CoA oxidase 1), and SCD (stearoyl-CoA desaturase) in diabetic nephropathy while suppressing the expression of FASN (fatty acid synthase)." (PMID 36091833, 2022).
multiple sclerosis (4 papers, 2022 to 2025). A progressive autoimmune disorder affecting the central nervous system resulting in demyelination. "Interestingly, SCD-1 is regulated by the diet, and SCD-1 deficiency in a mouse model of multiple sclerosis has recently been shown to promote regulatory T cell differentiation." (PMID 39841244, 2025). "It has been reported that in multiple sclerosis, myelin-induced elevation of Stearoyl-CoA desaturase-1 (SCD1) levels leads to a reduction in ABCA1 cell surface expression, affecting cholesterol efflux and promoting lipid accumulation." (PMID 39010173, 2024).
Abdominal obesity (3 papers, 2013 to 2025). Excessive fat around the stomach and abdomen. "In a previous study we found a genetic variant of the SCD-1 gene to be associated with the degree of abdominal obesity and insulin sensitivity in elderly men." (PMID 23298201, 2013).
acute hepatitis C (3 papers, 2021 to 2023). "A previous study has demonstrated that IFN-alpha regulated the expression levels of the SCD gene in the liver of primates, while it may have also enhanced the SCD activity in patients with acute hepatitis C." (PMID 35053107, 2022).
anaplastic thyroid carcinoma (3 papers, 2021 to 2023). "Stearoyl-CoA desaturase (SCD1) has been proved to be highly expressed in PTC, FTC and anaplastic thyroid carcinoma (ATC)." (PMID 36704039, 2022).
bladder tumor (3 papers, 2019 to 2025). "Taken together, these data suggest that SCD is highly expressed in bladder tumours and could be a reliable target for further investigations." (PMID 30592142, 2019).
Cirrhosis (3 papers, 2017 to 2019). A chronic disorder of the liver in which liver tissue becomes scarred and is partially replaced by regenerative nodules and fibrotic tissue resulting in loss of liver function. "Marker for stearoyl-CoA desaturase (SCD = ∆9-desaturase) activity i.e. palmitoleic: palmitic and oleic: stearic acid ratios, was found higher in HBV-cirrhotic patients, While PUFA: SFA was lower in HBV-cirrhosis patients as compared with control subjects." (PMID 28249586, 2017). "Indicators of stearoyl-CoA desaturase (SCD = ∆9-desaturase) activity, that is, the palmitoleic:palmitic acid (0.2) and oleic:stearic acid (1.5) ratios, were higher, while the PUFA:SFA ratio (0.6) was lower in HBV-related cirrhosis patients than in control subjects." (PMID 31726658, 2019). "Marker for stearoyl-CoA desaturase (SCD = ∆9-desaturase) activity i.e. palmitoleic: palmitic (0.2) and oleic: stearic acid (1.5) ratios, originated higher in HBV-cirrhotic patients, while PUFA: SFA (0.6) was lower in HBV-cirrhosis patients as compared with control subjects." (PMID 28249586, 2017).
COVID-19 (3 papers, 2023 to 2024). A disease caused by infection with severe acute respiratory syndrome coronavirus 2. "Therefore, ACOX2 and PECR may regulate the expression of SCD during the development of COVID-19, thus affecting the occurrence and development of AMD." (PMID 38625951, 2024). "However, our results suggest that SCD, the common core gene of lipid metabolism and inhibition of ferroptosis, may play a fundamental role in AMD, COVID-19 and tumor immunity." (PMID 38625951, 2024).
dry eye (3 papers, 2018 to 2024). "Since lipid abnormalities in the meibomian glands have been associated with dry eye, we analyzed selected eye tissues contributing to tear volume and composition in genetically SCD-1-deficient mice (SCD-1 KO), including the lacrimal glands and conjunctiva." (PMID 29463801, 2018). "Therefore, in this study, we aimed to ascertain the effect of meibomian gland abnormality on dry eye by analyzing tears and ocular tissue in SCD-1 KO mice." (PMID 29463801, 2018).
gestational diabetes mellitus (3 papers, 2020 to 2024). "MRNA expression of SREBP-1, SCD-1, ACC and FAS were increased in gestational diabetes rats, compared with those of normal pregnant rats (P < 0.01)." (PMID 33110438, 2020). "However, the administration of MPUFA or HPUFA suppressed the increase of SREBP-1, SCD-1, ACC and FAS mRNA expression in gestational diabetes rats of liver tissue (P < 0.05, P < 0.01)." (PMID 33110438, 2020).
periodontitis (3 papers, 2022). An acute or chronic inflammatory process that affects the tissues that surround and support the teeth. "In a rat model of periodontitis, SCD-1 was found markedly upregulated in the liver and associated with metabolic aberration." (PMID 35132337, 2022). "On the contrary, GDF15, SCD and TFAP2A had lower sensitivity in predicting periodontitis with T2DM, with AUCs of 0.54, 0.60 and 0.66, respectively." (PMID 36248844, 2022). "The genes with the highest degrees in shared-DEminRNA-gene network included PTEN, CCND1, MDM2, SCD, and TNRC6A, and these may be important miRNA-deregulated mediators linking H. pylori infection and periodontitis." (PMID 35132337, 2022).
prostate adenocarcinoma (3 papers, 2016 to 2025). "In prostate adenocarcinoma, elevated stearoyl-CoA desaturase (SCD) expression in malignant cells is positively associated with increased infiltration of CD8+ T cells and macrophages." (PMID 40270603, 2025). "In this study, the impact of SCD gene expression and the functional roles of the SCD protein in prostate adenocarcinoma (PRAD) were comprehensively analyzed using bioinformatic tools and functional experiments." (PMID 39351232, 2024).
prostate tumor (3 papers, 2017 to 2021). "Our data also identify, in prostatic tumor cells, a significant correlation between the expression of Myc and SCD-1 proteins, suggesting the existence of a potential functional relationship between the activities of these proteins in sustaining tumor progression." (PMID 28452935, 2017). "Since SCD-1 protein is increased in prostate tumors, we decided to analyze whether c-Myc and SCD-1 proteins are co-expressed in histological tumor samples from patients and control tissues using immunofluorescence assays." (PMID 28452935, 2017).
age-related macular degeneration (2 papers, 2020). Age-related loss of vision in the central portion of the retina (macula), secondary to retinal degeneration. "On the other hand, additional effects independently of its SCD inhibitory properties, involve anti-inflammatory and protective roles in retinal diseases such as age-related macular degeneration (AMD)." (PMID 31936134, 2020). "In addition, it displays anti-inflammatory properties, independently of SCD inhibition, which can be useful to treat other pathologies such as age-related macular degeneration (AMD)." (PMID 31936134, 2020). "Additional effects exerted by SA, independently of SCD inhibition, may be mediating anti-inflammatory and protective roles in retinal diseases such as age-related macular degeneration (AMD), but the mechanisms involved are poorly understood." (PMID 32403229, 2020).
aspergillosis (2 papers, 2014 to 2018). Aspergillosis is an infection, growth, or allergic response caused by the Aspergillus fungus. "Owing to significant safety level of SCD-1, it was investigated for in vivo antifungal efficacy using a mouse model of aspergillosis." (PMID 25140804, 2014). "SCD-1 demonstrated protection against infection by A. fumigatus in an intranasal murine model of aspergillosis." (PMID 25140804, 2014). "It was, concluded that SCD-1 for treating aspergillosis in animals was quite safe." (PMID 25140804, 2014). "Therefore, SCD-1 holds potential for developing new formulations for aspergillosis." (PMID 25140804, 2014).
autism spectrum disorder (2 papers, 2016 to 2024). A spectrum of developmental disorders that includes autism, and Asperger syndrome. "For instance, human CTTNBP2 (1663 amino acid residues) is a neuron-specific F-actin-associated SCD protein that is involved in the formation and maintenance of dendritic spines and it is associated with autism spectrum disorders." (PMID 38393970, 2024).
brain tumor (2 papers, 2021 to 2022). "Accordingly, SCD expression was higher in LGG compared to GBM, indicating a positive correlation between PTEN deletion and SCD expression in brain tumors." (PMID 33568479, 2021).
cardiac hypertrophy (2 papers, 2021 to 2023). "Immunohistological analysis revealed significantly increased cardiac SCD-Scd1 protein contents of 8-month-old male and female Tg-SCD mice with cardiac hypertrophy compared to age-matched, non-transgenic B6 mice (b and Figure A2)." (PMID 34576047, 2021).
E. coli infection (2 papers, 2018 to 2022). "The expression of genes and proteins related to fatty acid anabolism was downregulated by E. coli infection, including SREBP1, SCD, FAS, and PPARγ." (PMID 36341408, 2022).
endothelial dysfunction (2 papers, 2025 to 2026). In vascular diseases, endothelial dysfunction is a systemic pathological state of the endothelium (the inner lining of blood vessels) and can be broadly defined as an imbalance between vasodilating and vasoconstricting substances produced by (or acting on) the endothelium. "The observed alterations in lipid metabolism can be attributed to the upregulation of stearoyl-CoA desaturase-1 (SCD1) and the impairment of FADS1/2 and ELOVL2/5 activity, which in turn give rise to conditions conducive to inflammation, endothelial dysfunction, and plaque instability." (PMID 40564102, 2025).
gallstones (2 papers, 2021 to 2025). Solid crystalline precipitates in the biliary tract, usually formed in the gallbladder, resulting in the condition of cholelithiasis. "The stearoyl-CoA desaturase (SCD) inhibitor, Aramchol, initially used in gallstone treatment, has been shown to improve hepatic lipid accumulation in animal experiments, as well as in humans." (PMID 34444990, 2021).
Granuloma (2 papers, 2012 to 2024). A compact, organized collection of mature mononuclear phagocytes, which may be but is not necessarily accompanied by accessory features such as necrosis.
infertile (2 papers, 2017 to 2024). "Previous studies comparing SCD and TUNEL reported a good correlation between them and that both methods are similarly capable of distinguishing fertile and infertile men." (PMID 38674066, 2024).
ischemia (2 papers, 2021 to 2023). A hypoperfusion of the BLOOD through an organ or tissue caused by a PATHOLOGIC CONSTRICTION or obstruction of its BLOOD VESSELS, or an absence of BLOOD CIRCULATION. "Here, by an initial manual query, the expression levels of the following six proteins associated with the PPAR signaling cascade were found to be significantly altered after hepatic ischemia/reperfusion: SCD, Perilipin, FABP, ACS, APOA5 and PEPCK." (PMID 33407080, 2021).
morbid obesity (2 papers, 2021 to 2025). An excess of body weight, normally defined as an individual with a body mass index greater than 35 or a body weight greater than one hundred percent of ideal body weight. "In addition, we observed an upregulation of 10–30-fold for SCD, LIPIN1, and DGAT2 genes in low B12 primary Sc adipocytes derived from subjects with overweight and an increase of 20-fold for DGAT2 from subjects with morbid obesity (i–vi, p < 0.05)." (PMID 40264186, 2025).
osteoporosis (2 papers, 2020 to 2024). A condition of reduced bone mass, with decreased cortical thickness and a decrease in the number and size of the trabeculae of cancellous bone (but normal chemical composition), resulting in increased fracture incidence. "It is found that SCD is up‐regulated in skeletal muscle tissues of patients with osteoporosis." (PMID 32496000, 2020). "Herein, we first found the significant expression of PLEKHA2, PLEKHB1, PNPLA7, SCD, MGST3 and TSNAX in osteoporosis of postmenopausal women, which may be valuable in understanding the pathology mechanism of the disease." (PMID 32496000, 2020).
pancreatic duct adenocarcinoma (2 papers, 2015 to 2024). "Similar effects were observed in pancreatic duct adenocarcinoma (PDAC) cells where exposure to oleate also decreased FA production, irrespective of SCD inhibition, and inhibition of SFA production rescued toxicity of SCD inhibition, consistent with our model." (PMID 39187579, 2024).
psoriasis (2 papers, 2022 to 2026). An autoimmune condition characterized by red, well-delineated plaques with silvery scales that are usually on the extensor surfaces and scalp. "Finally, the increase in expression of SCD in lesional psoriasis skin likely accounts for the upregulation of unsaturated FAs (e.g., FA 18:1 and FA 18:2) in psoriasis." (PMID 35900871, 2022).
retinal diseases (2 papers, 2020). "In addition to SCD inhibition, it seems to exert most of its effects independently of its SCD inhibitory properties, which is particularly interesting in the treatment of retinal diseases because side effects could be greatly reduced by performing topic administrations." (PMID 32403229, 2020).